RTN1 (reticulon 1)
Description:
Inhibits amyloid precursor protein processing, probably by blocking BACE1 activity.
Synonyms: NSP
Tractability: Antibody: UniProt predicts a signal peptide or a membrane-spanning region. PROTAC: ubiquitination databases record sites on it; its protein half-life has been measured.
Gene: Protein-coding gene on chromosome 14 (59,595,976 to 59,870,796, reverse strand). Ensembl gene ENSG00000139970.
Subcellular location: Endoplasmic reticulum membrane; Golgi apparatus membrane
Subcellular location (Human Protein Atlas): Endoplasmic reticulum; Nuclear bodies
Gene Ontology:
Molecular function: protein binding
Biological process: negative regulation of amyloid-beta formation; brain development; endoplasmic reticulum tubular network formation; endoplasmic reticulum tubular network membrane organization; neuron differentiation
Cellular component: endoplasmic reticulum; endoplasmic reticulum membrane; Golgi membrane; neuron projection; postsynaptic density; dendrite; neuronal cell body
Genetic constraint (gnomAD): Loss-of-function variants: 25 observed, 56.19 expected, observed/expected ratio (o/e) 0.44, 90% interval 0.32 to 0.62. The upper end of that interval is the gene's LOEUF score, 0.62, which puts it in group 2 of 6, group 1 being the genes least tolerant of losing a copy. Missense variants: 974 observed, 950.14 expected, observed/expected ratio (o/e) 1.03, 90% interval 0.97 to 1.08. Synonymous variants: 468 observed, 407.95 expected, observed/expected ratio (o/e) 1.15, 90% interval 1.06 to 1.24.
Homologues: Orthologues: chimpanzee RTN1 (98% identical), macaque RTN1 (95% identical), pig RTN1 (85% identical), dog RTN1 (83% identical), mouse Rtn1 (82% identical), rat Rtn1 (82% identical), tropical clawed frog rtn1 (52% identical), zebrafish rtn1b (38% identical), guinea pig Rtn1 (26% identical), Drosophila melanogaster Rtnl1 (21% identical), Drosophila melanogaster Rtnl2 (8% identical). Paralogues in human: RTN4 (31% identical), RTN3 (24% identical), RTN2 (20% identical), PRR18 (5% identical).
Diseases named in the same sentence as RTN1 in open-access papers:
RTN1 is named in the same sentence as 35 diseases in open-access papers, as found by Europe PMC text mining. Sharing a sentence is not in itself a finding about the gene and the disease. The quoted sentences say what the papers report.
Alzheimer disease (4 papers, 2015 to 2020). A progressive, neurodegenerative disease characterized by loss of function and death of nerve cells in several areas of the brain leading to loss of cognitive function such as memory and language. "Our data suggest that RTN3 has a stronger association with Alzheimer’s disease (AD) pathology than RTN1, and this difference is likely related to unique sequences that are present in RTN1 and RTN3 as well as their differential localizations in neruites." (PMID 28733667, 2017). "The RTN1 gene encodes the RTN1C protein, which is a marker of neuronal differentiation and is known to be downregulated in patients with Alzheimer’s disease and Down syndrome." (PMID 25559585, 2015). "The physiological functions of RTN1 are largely unknown, but there are several reports linking RTN1 with neuropathophysiological conditions like Alzheimer ́s disease, cerebral ischemia and apoptosis." (PMID 33006503, 2020).
Cognitive impairment (2 papers, 2022 to 2024). Abnormal cognition is characterized by deficits in thinking, reasoning, or remembering. "We also found that 117 DEPs, including ADAM10, were closely associated to the AD‐specific β‐amyloid and tau pathologies; and the changes of IDH3B and RTN1 had a potential diagnostic value for cognitive impairment analyzed by machine learning." (PMID 36254251, 2022).
lung adenocarcinoma (2 papers, 2022 to 2025). A carcinoma that arises from the lung and is characterized by the presence of malignant glandular epithelial cells. "Previous studies have shown that RTN family members have an important influence on the development of lung diseases: RTN1 can act as a tumor suppressor gene and suggests a better prognosis for lung adenocarcinoma." (PMID 39972424, 2025). "We found that RTN1 expression was decreased in patients with lung adenocarcinoma and was closely related to patient prognosis." (PMID 35747917, 2022). "In this study, we aimed to investigate the expression of RTN1 in lung adenocarcinoma and its correlation with immune infiltration and survival in lung adenocarcinoma using public databases and bioinformatics network tools." (PMID 35747917, 2022). "However, the expression of RTN1 and its effect on the immune microenvironment in patients with lung adenocarcinoma have not been reported." (PMID 35747917, 2022).
lung carcinoma (2 papers, 2011 to 2016). "For instance, both the most negatively correlated gene, RTN1, involved in detoxification in lung cancer, and a potential lung cancer tumor suppressor, SEMA5A, were significantly down-regulated though frequently amplified in tumor tissues." (PMID 21935476, 2011).
osteosarcoma (2 papers, 2014 to 2019). A usually aggressive malignant bone-forming mesenchymal neoplasm, predominantly affecting adolescents and young adults. "We identified three genes located in focal gains and overexpressed in a significant fraction of both osteosarcoma sets: CD83 (6p23), RTN1 (14q23.1), and GPR177 (WLS/EVI) (1p31.3)." (PMID 25551557, 2014).
cognitive decline (1 paper, 2024). "Elevated levels of RTN1 in the blood during the preoperative period can indicate several underlying mechanisms that contribute to cognitive decline post-surgery." (PMID 39596303, 2024).
depression (1 paper, 2020). "Three replicated loci were previously reported (ITIH3, FHIT, BAG5), but the other seven (ZNF804A, MIR3143, PSORS1C2, STK19, SPATA31D1, RTN1, TCF4) were novel for depression." (PMID 30626913, 2020).
diabetes (1 paper, 2023). "Moreover, diabetes is a risk factor in both PCOS and UCEC, and HMOX1, RTN1, and KCNJ15 are considered diabetes-related genes." (PMID 37363398, 2023).
diabetic nephropathy (1 paper, 2015). "We found that RTN1 expression was higher in kidneys of patients with diabetic nephropathy (DN) compared with healthy controls." (PMID 26227493, 2015).
hepatoma (1 paper, 2016). "Here we report, based on transcriptome analysis, that RTN1-4 are simultaneously expressed, at different levels, in cultured hepatoma cells." (PMID 27786289, 2016).
hyperglycaemia (1 paper, 2015). "RTN1 overexpression in renal cells induces ER stress and apoptosis, whereas RTN1 knockdown attenuates tunicamycin-induced and hyperglycaemia-induced ER stress and apoptosis." (PMID 26227493, 2015).
ischemic stroke (1 paper, 2017). A stroke disorder caused by obstruction of blood flow to the brain, due to thrombotic (local blood clot formation) or embolic (due to a blood clot or other material traveling from another site) event. "Nin, Dact1, and Rtn1, which are located underneath the linkage peak and contain one or more nontolerated nonsynonymous SNPs, have shown suggestive associations with increased risk of ischemic stroke or lipoprotein particle size." (PMID 28040783, 2017).
melanoma (1 paper, 2020). A malignant, usually aggressive tumor composed of atypical, neoplastic melanocytes. "Only the module turquoise had a significant enrichment (p = 0.009) of genes whose homologs displayed prognostic value in melanoma, such as Oca2, Samhd1, Nlrc5, Irf1, Ifitm3, Sp100, Dram1, Rtn1, Tcaf2, Parp10, and Grin3a." (PMID 32831131, 2020).
minimal change disease (1 paper, 2015). "To further confirm the relevance of RTN1 in kidney disease, we performed RTN1 immunostaining on kidney biopsy samples of patients with minimal change disease (MCD), DN and HIVAN as well as normal kidney sections of nephrectomy samples." (PMID 26227493, 2015).
prostate carcinoma (1 paper, 2018). A carcinoma that arises from epithelial cells of the prostate gland. "For example,RTN1, a neuroendocrine cell specific protein, localized in endoplasmic reticulum, mightbe involved in the activation of the expression of androgen-responsive genes and relatedto prostate cancer." (PMID 29489999, 2018).
psychosomatic disorders (1 paper, 2025). "This review first outlines how epigenetic dysregulation contributes to psychosomatic disorders through altered expression of genes such as GRM2, TRPA1, SLC6A4, NR3C1, leptin, BDNF, NAT15, HDAC4, PRKCA, RTN1, PRKG1, and HDAC7." (PMID 41439979, 2025).
Senile plaques (1 paper, 2017). Senile plaques are extracellular deposits of amyloid in the gray matter of the brain. "Together, our data show that RTN1 and RTN3 have differential effects on the formation of senile plaques in Alzheimer’s brains and that RTN3 has a more prominent role in Alzheimer’s pathogenesis." (PMID 28733667, 2017).
viral infection (1 paper, 2019). "In the context of viral infection, deletion of RTN1 in yeast cells led to a significant inhibition of viral replication." (PMID 31892232, 2019).
cancer (8 papers, 2010 to 2025). A tumor composed of atypical neoplastic, often pleomorphic cells that invade other tissues. "RTN1 has been associated with neurological diseases (and cancer) and is thought to influence membrane trafficking in neuroendocrine cells." (PMID 24058735, 2013). "RTN1 plays a key role in membrane trafficking or neuroendocrine secretion of neuroendocrine cells, while RTN1 serves as a potential diagnostic/therapeutic marker for neurological diseases and cancer." (PMID 35747917, 2022). "The violin plot analysis revealed that most of the signature genes were predominantly expressed in cancer cells, with the exception of RTN1 and AREG, which exhibited higher expression in monocytes/macrophages." (PMID 37845218, 2023). "One SNV was identified downstream of RTN1 (reticulon 1), a biomarker for carcinomas with neuroendocrine characteristics and other cancers." (PMID 36011407, 2022). "For neurologic disorders and cancer, RTN1, an endoplasmic reticulum-related Reticulon gene, may serve as a diagnostic/therapeutic biomarker." (PMID 40375334, 2025). "Various roles of RTN1 in the biology of cancers have been previously investigated." (PMID 34702929, 2021).
tumor (8 papers, 2011 to 2026). "Although RTN1 relative mRNA level was decreased in tumour tissues from GES13911 dataset, it was almost unchanged in TCGA-STAD and GSE13861 datasets." (PMID 35428758, 2022). "Expression levels of RTN1 mRNA in tumor and normal tissues were analyzed using Tumor Immune Estimation Resource 2.0 (TIMER 2.0) and Gene Expression Profiling Interactive Analysis 2 (GEPIA 2)." (PMID 35747917, 2022). "In addition, We performed dimensionality-reduced clustering analysis at the single-cell sequencing level on two datasets from the Tumor Immune Single-cell Hub (TISCH) database to observe the cellular clustering of RTN1 in different types of immune cells." (PMID 35747917, 2022). "Crucially, we identified two previously under-characterized genes (RTN1 and TLR10) as potential novel drivers of tumor progression." (PMID 42186460, 2026). "High genomic alterations in zesto lesions were inversely correlated with putative tumor suppressor genes (MTUS2, DLGAP3, RTN1, CRLF1, SLC12A5, and PDIA2) and positively correlated with APOBEC mutagenesis (APOBEC3C, APOBEC3G, APOBEC3B, and APOBEC3F) and hypoxia-related gene signatures." (PMID 40319462, 2025).
kidney disease (4 papers, 2015 to 2022). "The reticulon 1 (RTN1) gene was the third most DM protein-coding gene in warts, with previous reports showing that RTN1 deficiency and isoforms were associated with senile plaque formation and kidney disease progression, respectively." (PMID 31892232, 2019). "In recent studies, we identified reticulon-1A (RTN1A), an ER-associated protein reticulon-1, as a novel gene associated with the progression of kidney diseases." (PMID 29340054, 2017). "Here the authors show that expression of Rtn1 can control severity of renal disease and that inhibition of its expression can attenuate ER stress and CKD." (PMID 26227493, 2015). "Previous studies have proven that overexpression of RTN1 induces ER stress by interacting with PERK and mediates the progression of kidney disease and kidney fibrosis." (PMID 35596061, 2022). "In the current study, we report that the expression of RTN1, specifically RTN1A isoform, is highly upregulated in both human and mouse models with kidney disease, and that its increased expression induces ER stress response and apoptosis in renal cells." (PMID 26227493, 2015). "In addition, RTN1 has never been studied in the context of kidney disease." (PMID 26227493, 2015).
neurological diseases (4 papers, 2013 to 2025). "Rtn1, a gene involved in membrane trafficking and regarded as a marker for neurological diseases, was downregulated in rotenone-exposed N27 cells, possibly mediated by HDAC4 downregulation." (PMID 39188570, 2024).
neurodegenerative disease (2 papers, 2020 to 2024). A disorder of the central nervous system characterized by gradual and progressive loss of neural tissue and neurologic function. "Other significantly downregulated genes were Resp18, Rtn1, Psap, Ubb, Aplp1, Cst3 and Itm2b, which are all associated with neurodegenerative diseases." (PMID 38017352, 2024). "Furthermore, we also identified the potential master transcriptional regulator RTN1, a protein that promotes endoplasmic reticulum-mediated apoptosis and is implicated in neurodegenerative diseases and cancer." (PMID 32080212, 2020). "Several genes involved in amyloid production were also found to be dysregulated by RH, including Aplp, Rtn1 and Itm2b, all of which have been associated with amyloid beta (Aβ) protein formation, and Resp18, Psap, Ubb and Cst3, all of which are associated with neurodegenerative diseases." (PMID 38017352, 2024).
RTN1 also shares sentences with these, for which no sentence is quoted: Cerebral ischemia (2 papers); breast carcinoma (1); carcinoid lung tumor (1); diffuse large B-cell lymphoma (1); Down syndrome (1); glioblastoma (1); glioma (1); lung diseases (1); neuroblastoma (1); polycystic ovary syndrome (1); renal fibrosis (1); schizophrenia (1).